TMEM170B (transmembrane protein 170B)
Description:
Negatively regulates the canonical Wnt signaling in breast cancer cells. Exerts an inhibitory effect on breast cancer growth by inhibiting CTNNB1 stabilization and nucleus translocation, which reduces the activity of Wnt targets.
Tractability: Antibody: UniProt places it where antibodies can reach, with high confidence; its Gene Ontology location is reachable by antibodies, with high confidence; UniProt predicts a signal peptide or a membrane-spanning region.
Gene: Protein-coding gene on chromosome 6 (11,537,748 to 11,583,524, forward strand). Ensembl gene ENSG00000205269.
Subcellular location: Cell membrane
Subcellular location (Human Protein Atlas): Centrosome
Gene Ontology:
Molecular function: protein binding
Biological process: negative regulation of canonical Wnt signaling pathway
Cellular component: plasma membrane
Genetic constraint (gnomAD): Loss-of-function variants: 6 observed, 12.13 expected, observed/expected ratio (o/e) 0.49, 90% interval 0.27 to 0.98. The upper end of that interval is the gene's LOEUF score, 0.98, which puts it in group 4 of 6, group 1 being the genes least tolerant of losing a copy. Missense variants: 124 observed, 146.77 expected, observed/expected ratio (o/e) 0.84, 90% interval 0.73 to 0.98. Synonymous variants: 57 observed, 56.27 expected, observed/expected ratio (o/e) 1.01, 90% interval 0.82 to 1.26.
Homologues: Orthologues: chimpanzee TMEM170B (100% identical), macaque TMEM170B (100% identical), pig TMEM170B (100% identical), dog TMEM170B (99% identical), mouse Tmem170b (98% identical), rat Tmem170b (97% identical), tropical clawed frog TMEM170B (89% identical), guinea pig TMEM170B (80% identical), zebrafish tmem170b (68% identical), Drosophila melanogaster CG12341 (37% identical), Caenorhabditis elegans F43G9.13 (27% identical). Paralogues in human: TMEM170A (48% identical).
Diseases named in the same sentence as TMEM170B in open-access papers:
TMEM170B is named in the same sentence as 10 diseases in open-access papers, as found by Europe PMC text mining. Sharing a sentence is not in itself a finding about the gene and the disease. The quoted sentences say what the papers report.
breast carcinoma (6 papers, 2018 to 2023). "TMEM170B expression is associated with the overall survival ratio in breast cancer patients." (PMID 33101375, 2020). "We have also analyzed the association of TMEM170B expression with the clinical overall survival (OS) ratio and associated pathological features to explore its prognostic and therapeutic value in preventing breast cancer progression." (PMID 29367600, 2018). "TMEM170B protein has been recognized as a negative regulator of the Wnt/β-catenin protumorigenic pathway in breast cancer." (PMID 37936608, 2023). "It was reported that the miR-27a downregulates TMEM170B in breast cancer and suggested a suppressor tumor role for TMEM170B." (PMID 37936608, 2023). "Transmembrane protein 170B (TMEM170B) has been reported to suppress breast cancer proliferation, metastasis, and tumorigenesis and is related to prognosis." (PMID 35601487, 2022). "Univariate and multivariate Cox regression analysis revealed that the pathological stage, TMEM170B and β-catenin expression were independent prognostic factors for OS in the breast cancer patients." (PMID 29367600, 2018). "We measured Wnt signaling in breast cancer cells after stable overexpression or knockdown of TMEM170B, which is a direct target of miR-27a, to investigate the regulation of TMEM170B on the Wnt/β-catenin pathway." (PMID 29367600, 2018). "Clinically, TMEM170B or β-catenin expression is significantly correlated with overall survival ratio in breast cancer patients." (PMID 29367600, 2018). "Future research efforts to design novel drugs to activate TMEM170B will provide a new therapeutic strategy to improve breast cancer treatment." (PMID 29367600, 2018). "We first examined the TMEM170B levels in different breast cancer cells by real-time PCR (RT-PCR) and immunoblotting to investigate the functional roles of TMEM170B in breast cancer progression." (PMID 29367600, 2018). "Knockdown of TMEM170B significantly induced the cell proliferation and colony-formation ability of breast cancer, whereas the overexpression of TMEM170B significantly impeded the breast cancer cells proliferation and colony-formation ability in vitro." (PMID 29367600, 2018). "We found that TMEM170B expression was more abundant in the normal tissues, while β-catenin expression occurred mainly in breast cancer tissues." (PMID 29367600, 2018). "Transmembrane protein 170B (TMEM170B), a new functional target of miR-27a, is identified via target prediction and experimental validation, suppressing breast cancer proliferation, metastasis, and tumorigenesis." (PMID 29367600, 2018). "In conclusion, our results revealed that TMEM170B, as a functional target of miR-27a, is important for balancing the deregulation of Wnt/β-catenin signaling in breast cancer." (PMID 29367600, 2018). "Furthermore, the overexpression of TMEM170B in the MDA-MB-231 cell line significantly impeded the breast cancer cells proliferation and colony formation." (PMID 37936608, 2023). "ARHGDIB, RERG, and TMEM170B were also related to breast cancer, implying they might participate in the development of mammary glands." (PMID 36685960, 2022). "In addition, MCF7 cells with stable TMEM170B knockdown were transfected with si β-catenin to explore the role of β-catenin in TMEM170B-mediated breast cancer progression." (PMID 29367600, 2018). "Our data strongly suggested that an elevated TMEM170B expression inhibited breast cancer progression and may be a clinical prognostic target in multiple malignant tumors." (PMID 29367600, 2018). "We then performed rescue experiments to determine whether miR-27a can functionally target TMEM170B, and to further demonstrate the importance of the miR-27a/TMEM170B axis in the progression of breast cancer." (PMID 29367600, 2018). "We first detected the effect of TMEM170B on the endogenous Wnt/TCF activity in breast cancer." (PMID 29367600, 2018).
breast carcinoma (continued). "We performed bioinformatics analysis of the data from the miRDB, Targetscan, Pictar, and miRanda websets to explore the molecular mechanism of miR-27a as an oncogenic molecule in breast cancer, and found that six genes are overlapped, namely TMEM170B, GPAM, PPAP2B, ST6GALNAC3, EYA1, and PPARG." (PMID 29367600, 2018). "Thus, understanding the function of TMEM170B and the signaling pathway connected with the miR-27a/TMEM170B axis are essential for the development of more effective strategies for treating breast cancer malignancy." (PMID 29367600, 2018). "In addition, overexpression of TMEM170B significantly slowed the cell migration and invasion of breast cancer cells in vitro, while miR-27a inhibitor prevented the cell migration, invasion, and wound-healing mediated by TMEM170B overexpression in MDA-MB-231 cells." (PMID 29367600, 2018). "We first determined that TMEM170B was significantly downregulated in conditions such as PAAD, breast cancer, oral cancer, ovary cancer, and thyrioid cancer." (PMID 35601487, 2022). "Additionally, TMEM170B was found to be significantly downregulated in pancreatic adenocarcinoma (PAAD), breast cancer, ovarian cancer, and thyroid cancer." (PMID 37936608, 2023). "Our analysis showed that miR-27a expression in TNBC patients was higher than that in non-TNBC patients, whereas TMEM170B levels in breast cancer patients with TNBC were lower than that in non-TNBC patients." (PMID 29367600, 2018).
pancreatic adenocarcinoma (2 papers, 2022 to 2023). "Association between TMEM170B expression and clinicopathological characteristics in 38 pancreatic adenocarcinoma patients." (PMID 35601487, 2022). "In this study, the expression status and prognostic value of transmembrane protein 170B (TMEM170B) in pancreatic adenocarcinoma were elucidated." (PMID 35601487, 2022).
pancreatic cancer (2 papers, 2022). "Other markers, such as AQP5, CDC25C, and TMEM170B, have been proved to be associated with the prognosis of pancreatic cancer." (PMID 35898870, 2022). "Hence, the present study aimed to investigate the role of TMEM170B as a prognostic biomarker and therapeutic target in pancreatic cancer and explore the possible underlying mechanisms of TMEM170B in the development of pancreatic cancer." (PMID 35601487, 2022). "In conclusion, this study is the first to confirm that human pancreatic cancer cells and tissues have decreased expressed of TMEM170B, which suggests that TMEM170B can serve as an independent prognostic predictor following surgery in patients with PAAD." (PMID 35601487, 2022). "The present study is the first to show that TMEM170B expression is significantly decreased in human pancreatic cancer cell lines and PAAD tissues." (PMID 35601487, 2022). "Immunostaining and real-time polymerase chain reaction (RT-PCR) were done to determine TMEM170B expression in human pancreatic cancer cell lines and tissue specimens." (PMID 35601487, 2022). "Our results revealed that TMEM170B expression was considerably lower in pancreatic cancer cell lines and tissues than in normal pancreatic duct epithelial cells and normal pancreatic tissues, respectively." (PMID 35601487, 2022). "Hence, TMEM170B can be a potential prognostic biomarker and immunotherapy agent in combination therapy regimens to improve pancreatic cancer treatment." (PMID 35601487, 2022). "Moreover, IHC and IF demonstrated that TMEM170B was localized in the plasma membrane and cytoplasmic regions of pancreatic cancer cells and that 63.2% of the pancreatic cancer tissue samples were TMEM170B positive." (PMID 35601487, 2022). "Therefore, TMEM170B could be regarded as a novel target in preventing the progression of pancreatic cancer." (PMID 35601487, 2022). "Therefore, TMEM170B is a potentially attractive therapeutic target for future anticancer drugs although its role in pancreatic cancer remains unknown." (PMID 35601487, 2022).
renal cell carcinoma (1 paper, 2018). "This study also identified that high expression of TMEM170B was negatively correlated with the poor prognosis of breast, uterine, and renal cell carcinoma patients." (PMID 29367600, 2018). "Interestingly, the lower expression of TMEM170B significantly decreased the OS ratio in human uterine (37% vs. 68%, P < 0.05) and renal cell carcinoma (69% vs. 88%, P < 0.05)." (PMID 29367600, 2018).
tumor (5 papers, 2018 to 2024). "It was observed in tumor center that the tumor tissue presented a high TMEM170B expression level, the infiltration Levels of CD4+T Cells, CD8+T cells was relatively active." (PMID 35601487, 2022). "Conversely, we observed that the MDSCs (labeled by CD11b+CD33+) was obviously recruited in tumor regions with low TMEM170B expression level." (PMID 35601487, 2022). "A histopathological comparison of the degrees of differentiation and TMEM170B expression of tumor tissues also indicates that low expression of TMEM170B in PAAD was correlated with less tumor differentiation." (PMID 35601487, 2022). "Tumor tissues were divided into low and high TMEM170B expression based on the median values of H-score of each core." (PMID 35601487, 2022). "We next investigate the effect of TMEM170B on the cell migration and invasion ability to further understand the tumor-suppressive role of TMEM170B." (PMID 29367600, 2018). "So far, we are observed that some TMEM proteins, such as TMEM48, TMEM45B, and TMEM168, are involved in tumor growth, proliferation, migration, and cell invasion through the Wnt/β-catenin pathway, while TMEM170B and TMEM98 act as cancer developmental inhibitors through the same pathway." (PMID 37936608, 2023). "Furthermore, TMEM170B, as a tumor suppressor gene, induced antitumor immune effects, including increased tumor infiltration of immune effector cells and reduced levels of inhibitory immune molecules and regulatory cells." (PMID 35601487, 2022). "The in vitro and in vivo results in the present study indicate that TMEM170B may be an endogenous tumor suppressor of BRCA, and play a critical role in multiple tumorigenesis processes, including proliferation, migration, and metastasis." (PMID 29367600, 2018). "However, other powerful in vivo models, such as dynamic live imaging with luciferase signal, which can track the metastatic colonization in real time would help better explain the importance of TMEM170B in tumor metastasis in vivo." (PMID 29367600, 2018). "It has been shown that some TMEM proteins are involved in tumor growth, proliferation, migration, and cell invasion through the Wnt/ b-catenin pathway, such as TMEM48, TMEM45B, and TMEM168, whereas TMEM170B and TMEM98 act as tumor development inhibitors through the same pathway." (PMID 38850316, 2024). "Tissue staining showed that TMEM170B had strong positive correlations with tumour-infiltrating CD4+ and CD8+ cells, and negative correlations with MDSCs." (PMID 35601487, 2022).
cancer (2 papers, 2018 to 2022). A tumor composed of atypical neoplastic, often pleomorphic cells that invade other tissues. "Patients and methods: We performed a comprehensive analysis of RNA sequencing data obtained from the Gene Expression Omnibus (GEO) and The Cancer Genome Atlas (TCGA) databases to determine TMEM170B expression." (PMID 35601487, 2022). "GENT2 tool was utilized to examine the mRNA levels of TMEM170B in pan-cancer tissues." (PMID 35601487, 2022). "Thus, in future studies, it will be interesting to investigate other (β-catenin-dependent) cellular processes and mechanisms by which TMEM170B exerts its suppressive effects on cancer." (PMID 29367600, 2018). "In addition, significantly lower TMEM170B levels have been found in some other types of human cancer compared to adjacent normal tissues (TCGA database)." (PMID 29367600, 2018). "Thus, TMEM170B could be regarded as a novel target to address cancer progression." (PMID 35601487, 2022). "Thus, TMEM170B could be regarded as a novel target in cancer progression." (PMID 29367600, 2018).
TMEM170B also shares sentences with these, for which no sentence is quoted: alcohol abuse (1 paper); breast (1); oral cancer (1); ovary cancer (1).